HCG18 (HLA complex group 18)
Diseases named in the same sentence as HCG18 in open-access papers (continued):
Sharing a sentence is not in itself a finding about the gene and the disease.
cancer (continued). "In vitro assays indicated that HCG18 promotes BC cell proliferation and invasion and endows BC cells with cancer stemness properties." (PMID 34976998, 2021). "The data further supported that HCG18 functioned as a cancer‐promoting factor in the progression of GC." (PMID 32725768, 2020). "Recent studies have demonstrated that lncRNA HLA complex group 18 (HCG18) might act as ceRNAs of numerous miRNAs and promote cancer progression through several signaling pathways." (PMID 38226210, 2024). "Additionally, investigations indicate the overexpression of HCG18 in exosomes released by these cells, leading to reduced expression of miR-424-5p in surrounding cancer cells." (PMID 39161590, 2024). "The results demonstrated that silencing HCG18 expression could inhibit cancer cells viability compared to the cells transfected with si-NC plasmid." (PMID 36854894, 2023). "Furthermore, through corresponding functional assays, indicated that SOX9 was an oncogene, overexpression of SOX9 altered the inhibition of cancer cell promotion mediated by lncRNA HCG18 knockdown through PI3K/AKT pathway." (PMID 36854894, 2023). "Knockdown HCG18 effectively inhibited cancer cells proliferation, migration and invasion." (PMID 36854894, 2023). "In the same way, knockdown HCG18 could mitigate cancer cell migration and invasion while add miR-424-5p inhibitor could alter this result, promoting cancer cell migration and invasion." (PMID 36854894, 2023). "Elevated HCG18 level could contribute to cancer proliferation, migration and invasion both in vivo and in vitro, reduce cancer cell apoptosis." (PMID 36854894, 2023). "Collectively, the evidence manifested that knockdown of lncRNA HCG18 could restrain cholangiocarcinoma cancer cells growth, migration, invasion and promote cancer cell apoptosis." (PMID 36854894, 2023). "What’s more, transwell and wound healing assays revealed that up-regulated SOX9 level could reverse the restrain of cancer cells migration and invasion brought by silencing HCG18." (PMID 36854894, 2023). "Increased HCG18 level could contribute to cancer proliferation, migration and invasion both in vivo and in vitro, reduce cancer cell apoptosis." (PMID 36854894, 2023). "The lncRNA HCG18 has been reported to participate in cell growth and metastasis in various cancers." (PMID 34991445, 2022). "There is a growing interest in how HCG18 regulates the biological processes of cancers." (PMID 35389764, 2022). "HCG18 has been identified as a carcinogenic gene in several cancer types." (PMID 34983361, 2022). "Of note, lncRNA HCG18 was identified as an oncogene in several human cancers, including LIHC." (PMID 36398067, 2022). "Long noncoding RNA HCG18 is known to play an important role in a variety of cancers." (PMID 34991445, 2022). "Moreover, adding miR-424-5p inhibitor in si-HCG18 group could restrain cancer cell apoptosis compared to si-HCG18 group." (PMID 36854894, 2023). "In our study, HCG18 was the only one lncRNA potentially competing with CD28, which had been reported to be relevant to immune cell infiltration in cancer." (PMID 34794447, 2021). "We found four lncRNAs that were directly or indirectly related to a variety of cancers, namely, TTC28-AS1, AC090425.1, LINC00092, and HCG18." (PMID 34615480, 2021). "Through CCK-8, EdU and colony formation assays, we found that increasing SOX9 level in si-HCG18-1 and SOX9 ov co-transfection group could facilitate cancer cell proliferation when compared to si-HCG18-1 group." (PMID 36854894, 2023). "A recent study showed that lncRNA HCG18 is overexpressed in LIHC tissues and could promote the proliferation and migration of cancer cell lines." (PMID 36398067, 2022).
HCG18 also shares sentences with these, for which no sentence is quoted: melanoma (2 papers); acute kidney injury (1); breast tumor (1); colon adenocarcinoma (1); colorectal neoplasm (1); head and neck squamous cell carcinoma (1); Hernia (1); kidney cancer (1); non-small cell lung carcinoma (1); nonalcoholic fatty liver disease (1); type 1 diabetes (1).